RALB (RAS like proto-oncogene B)
Diseases named in the same sentence as RALB in open-access papers (continued):
Sharing a sentence is not in itself a finding about the gene and the disease.
tumor (continued). "To understand how the loss of RALs in the tumor cells could impact the TME and thereby contribute to decreased tumor growth, we compared the secreted proteomes of the control and RALA or RALB depleted MDA-MB-468 cells." (PMID 39272901, 2024). "Following our observation that survivorship across BC, and especially in TNBC, is linked to the RALs, we herein explore the requirements of RALA and RALB in supporting cancer cell viability and tumor growth across a panel of BC cell lines with special focus granted to TNBC and HER2+ BC." (PMID 39272901, 2024). "RALA promoted the metastatic growth of TNBC cell lines, while RALB inhibited tumor metastasis." (PMID 36466919, 2022). "Interestingly, depletion of RALA increased the growth of 4T1 primary tumors, while depletion of RALB slowed primary tumor growth." (PMID 35626682, 2022). "RalA and RalB control lung tropism of pro-metastatic tumor extracellular vesicles (EVs)." (PMID 33404012, 2021). "Therefore, while depletion of RalA favors in vivo tumor growth by enhancing 4T1 proliferation potential, it is likely that additional non-cell autonomous factors are responsible for the decreased tumor growth observed upon RalB depletion." (PMID 33404012, 2021). "Compared to the profound effect of RALA and RALB depletion on in vivo tumor growth and metastasis, several common in vitro assays, including two-dimension invasion and viability assays, showed only modest effects or results which were inconsistent with in vivo tumor growth." (PMID 34118960, 2021). "We thus built on this relevant tumor model and decided to test the hypothesis that RalA and RalB could orchestrate pro-metastatic functions by tuning the molecular mechanisms driving the secretion levels and nature of EVs." (PMID 33404012, 2021). "Meanwhile, it is emphasized that the RalB/TBK1 pathway may activate an inflammatory response which can contribute to tumor promotion." (PMID 29047224, 2017). "Since the membrane attachment of Ccnd1 was able to appreciably improve the invasiveness of tumor cells, we tested whether the improvement in invasion was RalB-dependent." (PMID 27105504, 2016). "However, little emphasis has been made on comparison of individual roles of RalA and RalB and their downstream partners in tumor progression." (PMID 21714887, 2011). "When staining MDA-MB-468 tumors for the endothelial marker CD31, we found that RALB but not RALA loss decreased CD31 expression within both tumoral and stromal regions, suggesting that RALB may support angiogenesis in vivo and its silencing may impede tumor growth." (PMID 39272901, 2024). "Strikingly, RalB expression significantly increased in a manner consistent with disease progression: the median H-score was = 0.5 in normal juxtatumoral cells,=1 in tumor cells of in situ compartment,=1.5 in tumor cells of invasive compartment, and = 2 in tumor cells at lymph node metastasis." (PMID 30320548, 2018). "We also tested whether RalA or RalB could stimulate tumor growth in vivo." (PMID 21714887, 2011). "Furthermore, considering our observed changes in cytokine secretion following RALA and RALB loss in the MDA-MB-468 model, future experiments utilizing immunocompetent mice are needed to examine the role of the RALs in regulating the host anti-tumor immune response." (PMID 39272901, 2024). "have shown that RALA knockdown inhibits in situ tumor growth in TNBC cells, while RALB knockdown accelerates this process." (PMID 36466919, 2022). "Tumor invasion can also be promoted via Ras and its downstream pathways of MAPK and RALB, which were all shown to be upregulated in group 5." (PMID 35568708, 2022).
tumor (continued). "BQU57, a small molecule inhibitor of RALA and RALB, decreased TNBC cell line viability, sensitized cells to paclitaxel in vitro and decreased tumor growth and metastasis in TNBC cell line and PDX models in vivo." (PMID 34118960, 2021). "While the role of RALB in TNBC is slightly less clear, based on our findings, RALB appears to predominantly inhibit TNBC tumor growth and progression." (PMID 34118960, 2021). "To address this issue, we focused on the members of the Ral family, RalA and RalB (collectively referred to as RalA/B), acting downstream of RAS and promoting metastasis of different tumor types in both mice and human." (PMID 33404012, 2021). "It was found that RALA was required for the anchorage-independent proliferation of malignant cells whereas RALB was essential for tumor survival but not for non-malignant cells, making RALB a promising therapeutic target." (PMID 39857784, 2025). "Stable knockdown of either RALA or RALB decreased tumor growth in the TNBC MDA-MB-468 line but had no impact upon tumor growth in the HER2+ SKBR3 cell line." (PMID 39272901, 2024). "These in vivo data, along with previously published findings, support a critical role for RALA in TNBC tumor growth and progression as well as a critical role for RALB in some, but not all TNBC models." (PMID 39272901, 2024). "Neither RALA nor RALB were found to be required for primary tumor growth of PC3 cells but both paralogs contributed to bone metastasis." (PMID 35626682, 2022). "In addition, in tumor xenografts, unligated integrin αvβ3 interacts with galectin-3 at the plasma membrane, resulting in recruitment of KRAS and RalB." (PMID 35763345, 2022). "Importantly, indirect inhibition of RALB via the CDK5 inhibitor dinaciclib induced apoptosis in NRI-AML cell lines in vitro and reduced the tumor burden in AML PDX models in vivo." (PMID 35626682, 2022). "In addition, RalB downregulation prevents the growth of GBM cells in tumorspheres, suggesting that tumor stem cells are also affected." (PMID 35897776, 2022). "Two more CpG islands corresponding to genes PTPN4 and RALB were also analysed but remained unmethylated in all the normal and tumour samples (data not shown)." (PMID 19384295, 2009). "Here, stable knockdown of either RALA or RALB did not impact the orthotopic tumor growth." (PMID 39272901, 2024). "Importantly, inhibition of both RALA and RALB with the nonselective RAL inhibitor BQU57 significantly reduced tumor growth and metastasis in the TNBC cell line MDA-MB-231 and patient-derived xenograft models." (PMID 35626682, 2022). "Therefore, our findings demonstrate that DHA may act as a RalB inhibitor to regulate the crosstalk between autophagy and IFI16/caspase-1 inflammasome, which inhibits IL-1β production in tumor microenvironment." (PMID 32577124, 2020). "Thus, in tumor cells the RalB-Sec5-TBK1 pathway inhibits apoptosis, whereas in non-tumorigenic cells, it stimulates an innate immune response." (PMID 30791439, 2019). "In conclusion, we have shown that RALB inhibition regulates DR5 dynamics and induces apoptotic priming, and that targeting this apoptotic vulnerability with selective DR5-agonistic antibodies may be a promising strategy to improve treatment response in KRASMT CRC tumours." (PMID 33122623, 2020). "In contrast to the substantial negative effects on tumor growth observed when either RAL was silenced in the MDA-MB-468 cells, stable RALA and RALB silencing did not impact the in vitro or in vivo growth of the HER2+ cell line SKBR3." (PMID 39272901, 2024). "RALA, but not RALB, was required for MDA-MB-231 tumor growth, invasion, and metastasis." (PMID 35626682, 2022). "RALA, but not RALB, was found to be significantly upregulated in HCC relative to non-tumor tissues." (PMID 35626682, 2022).
cancer (32 papers, 2009 to 2025). A tumor composed of atypical neoplastic, often pleomorphic cells that invade other tissues. "RAL GTPases, encoded by RALA and RALB, are known for their roles in cell growth, granule secretion, and cancer metastasis." (PMID 38519457, 2024). "While both RALA and RALB have been implicated as drivers of aggressive phenotypes in many types of cancer, our study demonstrates a pro-tumorigenic and pro-metastatic role for RALA in TNBC which is not shared with RALB." (PMID 34118960, 2021). "RALA and RALB are small GTPases implicated in growth and metastasis of a variety of cancers, although little is known of their roles in BC." (PMID 34118960, 2021). "Here we reviewed the activation of TBK1 in cancer cells induced by multiple signaling components, such as RalB/Sec5/TBK1 complex, TBK1/TBKBP1/CARD10/PKC complex and TNFR1-SC complex." (PMID 39279883, 2024). "The variety and occasional discordance in the apparent roles of RALA and RALB both within and between cancer types suggest that diverse roles are commonly assumed by the two RALs in cancer." (PMID 39272901, 2024). "Careful and thorough validation of antibodies and targeting RNAs is imperative if we are to unravel the independent functions of RALA or RALB across cancer." (PMID 35626682, 2022). "This study paid particular attention to a highly scoring locus, near which are a transcription factor required for suppression of apoptosis (RALB) and a downregulated non-coding RNA (LOC84931, which is associated with poor survival from cancer)." (PMID 35269927, 2022). "Here we review the structure, regulatory mechanisms and post-translational modifications of RALA and RALB to gain insight into the structural basis for their conserved and contradictory functions in cancer." (PMID 35626682, 2022). "In this review we highlight the overlapping and divergent roles of RALA and RALB in cancer, describe their effectors, examine their potential as therapeutic targets, and provide important considerations for future RAL-GTPase research." (PMID 35626682, 2022). "In this study, we provide evidence that the RALB-GTPase is an important regulator of RASMT cancer cell survival and that inhibition of RALB ‘primes’ KRASMT cells to death upon stimulation with DR5-agonistic antibodies." (PMID 33122623, 2020). "Very interestingly, RalB (but not RalA) protein expression increased in a manner consistent with disease progression (normal < in situ < invasive < metastatic tissues), supporting once more a crucial role for RalB in cancer invasion and metastasis." (PMID 30320548, 2018). "The two Ral GTPases, RalA and RalB, have crucial roles downstream Ras oncoproteins in human cancers; in particular, RalB is involved in invasion and metastasis." (PMID 30320548, 2018). "We therefore examined the role of RalA and RalB in regulating Arf6 in K-Ras expressing pancreatic (MiaPaCa2) and H-Ras expressing bladder (T24) cancer cells." (PMID 27269287, 2016). "Ral GTPases are also activated in Ras-independent cancers through other mechanisms.Ral isoforms, RalA and RalB, though 82% identical regulate distinct cellular functions in normal and cancer cells." (PMID 27269287, 2016). "RalA and RalB have antagonistic effects on cancer cell migration, but possess overlapping functions in cell growth." (PMID 22442671, 2012). "KARS activates TBK1 through RALB to promote cancer cell survival." (PMID 40478912, 2025). "This work highlights the sometimes paradoxical roles of RALA and RALB in cancer." (PMID 35626682, 2022). "For those contributing to RAL-related cancer research, it is critical that studies rigorously address the contribution of both paralogs and account for potential confounding effects caused by the substantial similarities between RALA and RALB." (PMID 35626682, 2022). "RALA and RALB are small GTPases related to the growth and metastasis of various cancers." (PMID 36466919, 2022).
cancer (continued). "However, despite decades of study, the functions of RALA and RALB in normal cell and cancer biology remain incompletely understood." (PMID 35626682, 2022). "RALA and RALB can have redundant, unique, or even antagonistic functions depending on cancer type." (PMID 35626682, 2022). "Previous studies showed that RALA and RALB might play distinctive oncogenic roles in human cancers, as RALB contributed to the survival of human cancer cells." (PMID 35409173, 2022). "Furthermore, it has been shown that in cancer cells with stem-like properties, RALB is recruited by the αvβ3 integrin to the plasma membrane together with KRAS and NF-κβ." (PMID 34359657, 2021). "DHA treatment induced autophagy leading to the reduction of RalB/USP33 expression in cancer cells." (PMID 32577124, 2020). "Overall, these findings indicate that the role of RalB protein in human cancers is larger than previously thought, and they highlight a new pathway that could be a target for new anti-cancer drugs." (PMID 30320548, 2018). "Similarly, inhibition of BCL2 family proteins with ABT-737 or ABT-199 suppressed the clonogenic potential of de novo NRD AML and relapsed NRI AMLs, consistent with the established role of BCL2 proteins to support cancer cell survival downstream of RALB." (PMID 27991934, 2017). "RalB can however also contribute to anchorage independence in some cancers." (PMID 27269287, 2016). "Globally, these findings provide a novel mechanistic insight on how RalB contributes to force-driven cancer invasion and dissemination and suggest that RalB function may be particularly crucial after EMT." (PMID 26152517, 2015). "In addition, a better understanding of the full spectra of post-translational modifications of RALA and RALB and how these modifications alter subcellular localization and effector utilization is required to provide a framework for their various roles in cancer." (PMID 35626682, 2022). "However, the scientific evidence regarding the role of RALB in cancer is controversial." (PMID 34359657, 2021). "Therefore, RalB inhibitors represent developing novel agents for cancer therapy." (PMID 32577124, 2020). "In cancer cells, TBK1 activity was shown to be regulated through the RalB–GTPase pathway, coupling innate immune signaling with cancer phenotypes." (PMID 40738190, 2025). "In addition to supporting cancer cell survival, the RalB/Sec5/TBK1 cascade is also required for IRF3 nuclear translocation and Sendai virus-induced IFN-β promoter activation, suggesting that RalB/Sec5 effector complex, as an oncogenesis driver, could also be part of innate immune signaling." (PMID 39279883, 2024). "Depletion or knockout of RALGAP1 or RALGAP2 increases invasion and migration of cancer cells, with a concomitant increase in RALA or RALB activation." (PMID 35626682, 2022). "Downregulation of several RALGEFs has been shown to decrease the invasion and migration of cancer cells both in vitro and in vivo through decreased RALA or RALB activity." (PMID 35626682, 2022). "In this study, it was shown that DHA reduced the expression level of RalB and USP33 in three different types of cancer cells." (PMID 32577124, 2020). "Given the frequently non-redundant roles of RALA and RALB in cancer, the development of paralog-specific inhibitors would provide the field with invaluable research tools and potentially powerful therapeutics." (PMID 35626682, 2022). "Despite the striking similarities between RALA and RALB protein structure, overlapping GAP and GEF utilization, and a shared pool of downstream effectors, the RAL isoforms demonstrate unexpected disparity, even antagonism, of function in various cancers." (PMID 34118960, 2021). "Despite similarities between RALA and RALB in terms of protein structure, overlapping GAP and GEF utilization, and a shared pool of downstream effectors, the two protein isoforms often exhibit distinct biological functions in many cancers." (PMID 34118960, 2021).
cancer (continued). "Meanwhile, multiple studies reported that Ras-driven transformation depends on RalA and not RalB in various human cancer cell lines." (PMID 31201267, 2019). "Our work suggests that inhibition of the activity of RalB or GEF-H1, by decreasing contractility-driven dissemination, could have a therapeutic anti-metastatic benefit for cancer patients." (PMID 26152517, 2015). "Indeed, RalA and RalB have antagonistic effects on cancer cell migration and RalA but not RalB drives delivery of membrane proteins to the basolateral surface of epithelial cells." (PMID 19890390, 2009). "In this review we examine the functions of the RAL paralogs in normal cellular physiology and cancer biology with special consideration provided to situations where the roles of RALA and RALB are non-redundant." (PMID 35626682, 2022). "BQU57 and its related compounds directly target both RAL isoforms non-electively which may limit their usefulness in cancers where RALA and RALB have antagonistic roles." (PMID 34118960, 2021).
infection (2 papers, 2020 to 2021). The state of being infected such as from the introduction of a foreign agent such as serum, vaccine, antigenic substance or organism. "Differential activation of autophagy and MTORC1 by SQSTM1/p62TRM, TBK1, TRAF6 and RALB, which are among the prominent molecules involved in both pathways, needs to be studied further in disease and/or infection-relevant settings." (PMID 32627660, 2021). "RALB, which also controls starvation-induced autophagy, is thus co-opted during infection for xenophagy or IFN production." (PMID 32627660, 2021). "RalGAPs are involved in the negative regulation of RalGTPases, RalA and RalB, in the Ras/Ral signaling pathways and regulate crucial cellular processes including response to infection and mediation of inflammation." (PMID 32414370, 2020).
RALB also shares sentences with these, for which no sentence is quoted: breast tumor (1 paper); cardiovascular disease (1); colitis (1); depression (1); hematological disease (1); hepatocellular carcinoma (1); laryngeal squamous cell carcinoma (1); lymph node metastasis (1); major depression (1); neurodegenerative disease (1); pancreatic adenocarcinoma (1); rectal tumor (1).